CRLF2 (cytokine receptor like factor 2)
Diseases named in the same sentence as CRLF2 in open-access papers (continued):
Sharing a sentence is not in itself a finding about the gene and the disease.
leukemia (continued). "Moreover, we demonstrated that while mutant Jak2 can cooperate with Crlf2 to drive development of leukemia in mice, genetic depletion or pharmacological inhibition of Jak2 served merely to delay proliferation of the leukemias, resulting in a modest therapeutic response in vivo." (PMID 29907650, 2018). "However, consistent with the apparent global up-regulation of Myc target genes in chronic Jak2 knockdown Eμ-Crlf2/Jak2R683G cells, c-Myc protein levels were prominently up-regulated in Eμ-Crlf2/Jak2R683G leukemia cells following sustained Jak2 depletion (shJak2.3323, C#8 M7 and M8)." (PMID 29907650, 2018). "In CRLF2 B-ALL, TSLP plays a dual role in leukemia cell proliferation, closely related to its dosage." (PMID 40787610, 2025). "Currently, there is no commercial system available for the direct detection of the IGH::CRLF2 fusion by fluorescent in situ hybridization (FISH), as there are for many other leukemia-related gene fusions." (PMID 37574565, 2023). "Treatment of these leukemias with CHZ868 resulted in apoptosis; however, we demonstrate that this compound remained potent even in JAK2-depleted CRLF2/JAK2 mutant B-ALLs, indicating a putative off-target effector mechanism." (PMID 29907650, 2018). "Here, we developed novel GEMMs of human B-ALL through transgenic overexpression of Crlf2 and concomitant expression of mutant Jak2 to determine the role of mutant JAK2 in leukemia initiation and maintenance of disease." (PMID 29907650, 2018). "Thymic stromal-derived lymphopoietin (TSLP), the ligand binding to CRLF2, induces leukemia proliferation involving mTOR signaling and cases of Ph-like ALL with aberrant CRLF2 expression displayed increased mTOR signaling activity." (PMID 25682198, 2015). "In this study we investigated whether treatment of pre-clinical models of CRLF2 B-ALL, both cell lines and PDXs, with increasing concentrations of TSLP has major effects on leukemia cell survival in vitro and leukemia burden in vivo." (PMID 36613920, 2022). "It will be important to explore whether this is also the case for CRLF2 to better understand the mechanism of activity of CRLF2 in T-ALL pathology and to develop strategies for effective leukemia eradication." (PMID 27449287, 2016). "Thus, administering high levels of TSLP may offer a novel therapeutic strategy for treating CRLF2 B-ALL, providing new insights into clinical leukemia treatment." (PMID 40787610, 2025). "Similarly, knockdown of Jak2 in Eμ-Crlf2/Jak2P933R B-ALLs also resulted in enhanced survival of recipient mice, although not to the same extent as seen using Eμ-Crlf2/Jak2R683G leukemias." (PMID 29907650, 2018). "Our results suggest that, although a direct targeting of CRLF2 on cell surface is not feasible in T-ALL, the downstream JAK/STAT5 signaling could be a potential target for the therapy of this high risk leukemia subgroup." (PMID 27449287, 2016). "Strikingly, this IGH germline ALL group exhibited a high frequency of IKZF1 deletions and non-V(D)J rearrangements including CRLF2-IGH, EPOR-IGH, and EBF1-PDGFRß that can be exploited as leukemia-specific targets in clinical diagnostics of MRD." (PMID 31784504, 2019). "However, CRLF2 knockdown in the B-ALL cell line MUTZ5 only partially abrogated cell proliferation and CRLF2 expression in primary bone marrow progenitor cells did not result in leukemia development in vivo." (PMID 34066732, 2021).
Down syndrome (16 papers, 2012 to 2026). "This could be explained by the reported low frequency of CRLF2 pathogenic variants in pediatric cohorts, which is approximately 2%, and the higher co-occurrence (about 10%) between JAK2 variants and CRLF2-r in non-Down Syndrome ALL." (PMID 38370004, 2024). "P2RY8::CRLF2 was found in four cases, three of them with Down syndrome, consistent with prior reports." (PMID 41561684, 2026). "Rearrangements or mutations in cytokine receptor-like factor 2 (CRLF2), located at the pseudo-autosomal region (PAR1) at Xp22.3/Yp11.3, occur in up to 7% of B-ALL cases and in almost 50% of Down syndrome-associated (DS-associated) B-ALL cases." (PMID 40002837, 2025). "CRLF2 rearrangements and activating JAK mutations also occur in 50–60% of Down-syndrome-associated ALL (DS-ALL) cases." (PMID 39681640, 2025). "Patients with IGH‐CRLF2 were older (14 y vs. 4 y, P < .001), while the incidence of CRLF2‐r among Down syndrome patients was high (50/161, 31%)." (PMID 28033648, 2017). "Notably, CRLF2/JAK alterations are also very common in ALL patients with Down syndrome, but these children have been excluded from ruxolitinib-based clinical trials to date." (PMID 41154380, 2025). "Rearrangements involving cytokine receptor-like factor 2 (CRLF2) gene (CRLF2r) have been identified in approximately 10 % of pediatric BCP-ALL, but their incidence increases to approximately 50 % in children with Philadelphia-like (Ph-like) BCP-ALL, and in Down syndrome (DS)-associated BCP-ALL." (PMID 39071567, 2024). "In a mouse model of Down syndrome and in DS-ALL patient samples, CRLF2 overexpression leads to reduced B-cell differentiation and enhanced E2F signaling." (PMID 40787610, 2025). "Overall, the frequency of CRLF2 rearrangements in B-ALL is approximately 5% and the rate gets higher in cases without canonical B-ALL alterations (10–30%) and in patients with Down syndrome (> 50%)." (PMID 33781217, 2021).
B-cell acute lymphoblastic leukemia (11 papers, 2018 to 2025). A neoplasm of lymphoblasts committed to the B-cell lineage, typically composed of small to medium-sized blast cells. "Another study demonstrated that poor outcomes in pediatric B-cell acute lymphoblastic leukemia are associated with high levels of CRLF2 gene expression across distinct molecular subtypes." (PMID 40787610, 2025). "Studies have assessed CRLF2 expression in various cohorts of pediatric and adult patients with B-cell acute lymphoblastic leukemia (B-ALL) and found significant prognostic associations." (PMID 40787610, 2025). "CRLF2 overexpression has been widely confirmed to be associated with adverse outcomes in B cell acute lymphoblastic leukemia (B-ALL)." (PMID 38566223, 2024). "The gene fusions BCR‐ABL1, TCF3‐PBX1, and ETV6‐RUNX1 are recurrent in B‐cell acute lymphoblastic leukemia (B‐ALL) and are found with low frequency in coexistence with CRLF2 (cytokine receptor‐like factor 2) rearrangements and overexpression." (PMID 33890726, 2021).
B-cell precursor acute lymphoblastic leukemia (8 papers, 2015 to 2025). "CRLF2 gene alterations have been observed to correlate with poor prognosis in Japanese BCR-ABL1-negative high-risk B-cell precursor acute lymphoblastic leukemia, which suggests that the downregulation of CRLF2 may block the inflammatory effect of nickel ions." (PMID 26044615, 2015). "In adult patients with B-cell precursor acute lymphoblastic leukemia, high CRLF2 expression was also associated with higher white blood cell (WBC) counts, the presence of P2RY8-CRLF2 fusion, and IKZF1 deletions (IKZF1del)." (PMID 40787610, 2025).
T-cell acute lymphoblastic leukemia (4 papers, 2016 to 2025). Acute lymphoblastic leukemia of T-cell origin. "Aberrant signaling due to gain of function mutations in the IL-7Rα gene has been shown to promote the survival of T-cell ALL (T-ALL), especially when associated with cytokine receptor-like factor 2 (CRLF2), another gene mutation associated with pediatric ALL." (PMID 34830969, 2021).
asthma (2 papers, 2008 to 2023). "The TSLPR, also known as CRLF2, is expressed in heart, skeletal muscle, kidney and liver, but also on asthma-relevant dentritic cells." (PMID 18724870, 2008).
colitis (2 papers, 2021 to 2022). Inflammation of the colon. "Several genes such as Gata3, Itk, Ccl8, Ccl22, Ccr4, Crlf2, Il9r, Il1rl1, and Arg2 are regulated concordantly in T-cell transfer colitis, acute DSS colitis and the time point representing high inflammation in the DSS time course." (PMID 34136502, 2021).
lymphoma (2 papers, 2021 to 2025). A malignant (clonal) proliferation of B- lymphocytes or T- lymphocytes which involves the lymph nodes, bone marrow and/or extranodal sites. "B-lymphoblastic leukemia/lymphoma with BCR::ABL1-like features exhibits a CRLF2 gene rearrangement in 50% of cases, leading to an overexpression of CRLF2 protein, which can be assessed by flow cytometric analysis." (PMID 40227608, 2025).
Splenomegaly (2 papers, 2016 to 2018). Abnormal increased size of the spleen. "We also observed that the high CRLF2 expression group had a higher frequency of splenomegaly (58.6% vs. 27.8%, P = 0.012), indicating extramedullary infiltration." (PMID 27391346, 2016). "A subset of recipient mice transplanted with Eμ-Crlf2 FLCs expressing Jak2 mutants (Jak2R683G and Jak2P933R) succumbed to disease with outgrowth of GFP+ populations in the spleen and bone marrow and elevated peripheral white blood cell (WBC) counts and/or splenomegaly." (PMID 29907650, 2018).
airway hyperresponsiveness (1 paper, 2023). "Of those dysregulated genes, four were associated with immune-mediated inflammatory diseases (Csf2; Crlf2; Rnase2b; Tpsb2) and one with airway hyperresponsiveness (Prg2), while Il-13 was associated with both of those pathways." (PMID 36834405, 2023).
breast tumor (1 paper, 2022). "IL-3 and GM-CSF receptor genes (IL3RA, CSF2RA, and CSF2RB) were expressed in human normal mammary epithelial and breast tumor cells at markedly higher levels compared with TSLP receptor (CRLF2)." (PMID 35657353, 2022).
eosinophilia (1 paper, 2018). "Similar to Il33−/− mice, Il25−/− mice and Crlf2−/− mice showed attenuated airway eosinophilia after FAP inhalation, suggesting that IL-25 and TSLP, in addition to IL-33, are involved in FAP-induced airway eosinophilia." (PMID 30575775, 2018).
HIV-1 infection (1 paper, 2015). The type species of lentivirus and the etiologic agent of acquired immunodeficiency syndrome (AIDS). "Thus, it appears that the CRLF2 gene expression went from downregulated in early infection to significantly upregulated in the late HIV-1 infection." (PMID 26426037, 2015).
influenza infection (1 paper, 2021). "(D) Percentage of P14 WT and Crlf2-/- T cells at day 8 p.i. with influenza in BAL fluid, lungs, LN, and spleen (combined data from three independent experiments are shown)." (PMID 33439121, 2021). "(G) Heatmap of differentially expressed genes from WT or Crlf2-/- CD8+T cells at day 8 p.i. with secondary influenza infection." (PMID 33439121, 2021). "(C) Representative flow cytometry plots showing the percent of transferred P14 cells (gated on live lymphocytes) and proportion of WT and Crlf2-/- cells within the transferred population at day 8 p.i. with influenza in the tissues." (PMID 33439121, 2021). "Here, we found that TSLP acts directly on CD8+ T cells to limit their responses in most tissues during primary influenza infection, with more virus-specific Crlf2-/- cells than virus-specific WT cells." (PMID 33439121, 2021). "Interestingly, RNA-Seq data indicated that TSLP suppresses several genes that are related to cell cycle, apoptosis, or protection from virus in influenza infection, with an increased number of virus-specific Crlf2-/- CD8+ T cells." (PMID 33439121, 2021). "Importantly, TSLP limited memory CD8+ T cell recall responses, with enhanced cellular responses in multiple tissues of Crlf2-/- T cells following either secondary influenza infection or LCMV systemic infection." (PMID 33439121, 2021). "Each mouse was then infected with influenza PR8-33 i.n. for >30 days, and WT P14 cells and Crlf2-/- P14 cells were separately isolated." (PMID 33439121, 2021). "One study using Crlf2-/- mice indicated that TSLP does not affect the control of influenza infection nor affect virus-specific CD8+ T cell responses during primary infection." (PMID 33439121, 2021).
lymphoid leukemia (1 paper, 2016). A malignant lymphocytic neoplasm of B-cell or T-cell lineage involving primarily the bone marrow and the peripheral blood. "Given that the regulatory element of P2RY8 is highly active in lymphoid cells, it is fitting that the P2RY8-CRLF2 rearrangement, which places the proto-oncogenic CRLF2 under control of the P2RY8 regulatory element, is correlated with lymphoid leukemia." (PMID 27655702, 2016).
mantle cell lymphoma (1 paper, 2016). Mantle cell lymphoma is a rare form of malignant non-Hodgkin lymphoma affecting B lymphocytes in the lymph nodes in a region called the ``mantle zone''. "LOH in a region of the PAR, which results in deletion of SHOX, CRLF2, and CSF2RA, has been observed in mantle cell lymphoma." (PMID 27655702, 2016). "Conversely, LOH of CSF2RA, along with SHOX and CRLF2, due to deletion in a portion of the PAR has been reported in mantle cell lymphoma." (PMID 27655702, 2016).
melanoma (1 paper, 2022). A malignant, usually aggressive tumor composed of atypical, neoplastic melanocytes. "Indeed, examination of CRLF2 gene expression in CD4+ T cells from human melanoma scRNA-seq data did not reveal higher expression of CRLF2 by GATA3+ Tregs compared with other CD4+ T cells." (PMID 36107619, 2022).
Obesity (1 paper, 2025). Accumulation of substantial excess body fat. "Additionally, rs3824662 is associated with adipogenesis, since Hispanic patients have a high prevalence of obesity and overweight, it has been suggested that obesity predisposes to CRLF2-ALL." (PMID 40421094, 2025). "An independent study showed that Hispanic patients with CRLF2 rearrangements had higher obesity rates than those without CRLF2 lesions." (PMID 40421094, 2025).
tumor (14 papers, 2014 to 2025). "For instance, CRLF2 upregulation promotes tumor progression, while HSP90AA1 is linked to chemoresistance." (PMID 37897503, 2023). "It has been shown that high-dose of thymic stromal lymphopoietin (TSLP) can induce apoptosis, impeding the proliferation and migration of CRLF2 B-ALL tumor cells." (PMID 38566223, 2024). "The CK2 inhibitor, TBB, which restores IKZF1 tumor suppressor activity, increased the suppression of CRLF2 expression and IKZF1 knockdown blocks the TBB-induced changes." (PMID 27391346, 2016). "Provided the relatively low incidence of the single gene mutations, clonal mutations (detected in >20% of tumor population) were grouped into the JAK/STAT (IL7R, JAK2, JAK1, CRLF2 mutations and CRLF2-rearrangements) and RAS/RTK (FLT3, KRAS, NRAS) pathways." (PMID 26883104, 2016). "CD4+ T cells were sorted from tumors and tumor-draining lymph nodes of Tslp-PyMttg (test) or MMTV-PyMTtg, Tslpr(Crlf2)−/− (PyMttg TslprKO; control) mice and stimulated ex vivo using anti-CD3/CD28 antibodies plus TSLP over one to three cycles." (PMID 35657353, 2022). "To investigate whether the tumor-promoting effect of TSLP involves signaling through TSLPR expressed by DCs, we generated mice with the ablation of TSLPR selectively in DCs by breeding mice bearing the floxed allele of the Crlf2 gene with CD11c-Cre transgenic mice." (PMID 36107619, 2022). "Secondary alterations affecting cytokine signalling occurred in 37% iAMP21 of tumours (QBinomial = 2.2 × 10−3) involving IL7R, JAK2 or CRLF2 (including 3/5 cases of P2RY8-CRLF2 translocation)." (PMID 34753926, 2021). "In both CRLF2-re PDX, spleen weights were significantly reduced by ruxolitinib alone or when combined with mTOR inhibitors, and most pronounced in the BBT594/AZD2014 combination group, indicating significant reduction of total tumor burden." (PMID 29487712, 2018). "Advances in cytogenetics utilizing array-based technologies and NGS have uncovered additional submicroscopic DNA alterations affecting genes involved in normal hematopoiesis, tumor suppression, apoptosis, and cell cycle regulation, including IKZF1, CRLF2, PAX5, and FLT3." (PMID 24949228, 2014). "However, the deletion leading to the fusion of P2RY8 and CRLF2 also results in the deletion of several genes (P2RY8, CSF2RA, IL3RA, SLC25A6, and ASMTL) whose potential roles as tumor suppressors should not be discounted." (PMID 27655702, 2016).
cancer (10 papers, 2011 to 2025). A tumor composed of atypical neoplastic, often pleomorphic cells that invade other tissues. "Screening 107 overall survival-related cancer genes and 402 interacting gene pairs, 6 genes: CRLF2, HSP90AA1, MAP2K1, PAFAH1B2, MYCL and SET genes, were identified and a transcriptional score was obtained." (PMID 37897503, 2023). "Within this set of genes, a subset, notably CSF2RA, CRLF2, IL1R1, IL7R, and PDGFRB, exhibited intricate connections with the JAK-STAT pathway, which is crucial for the viability of cancer cells." (PMID 38743676, 2024). "CRLF2 overexpression activates the JAK/STAT pathway and therefore represents a potential target for JAK inhibitors in cancer therapy." (PMID 29899835, 2018). "If increased AID activity is resulting in CRLF2 instability and driving CRLF2::IGH translocations, we also wanted to know if this is detected in samples from healthy, cancer-free donors as this may be a prognostic feature of Ph-like ALL." (PMID 39068148, 2024).
infection (5 papers, 2015 to 2025). The state of being infected such as from the introduction of a foreign agent such as serum, vaccine, antigenic substance or organism. "Infection associated receptor encoding genes include CCR1 (encoding a receptor for CCL5), CRLF2 (cytokine receptor like factor 2), IL10RA, TLR2, CD2, CD48 and IL7R." (PMID 35061738, 2022). "In contrast, however, we observed differences after systemic acute LCMV infection, with increased Crlf2-/- virus-specific cells in the blood and lymph nodes at a memory time point post-infection." (PMID 33439121, 2021). "The upregulation of IL13RA1, OSMR, CRLF2, and IL6R in our study may indicate responses to maintain neuromuscular integrity under infection-induced stress." (PMID 40943072, 2025).
genetic disorder (1 paper, 2017). "In this Taiwanese family, three genes (CSF2RA, CRLF2, and IL3RA) are homozygously deleted in the pseudoautosomal region of the human X chromosome, concordant with that PAP is a rare genetic disorder inherited at a recessive pattern." (PMID 28233860, 2017).
CRLF2 also shares sentences with these, for which no sentence is quoted: breast carcinoma (2 papers); Allergy (1); brain tumors (1); central nervous system leukemia (1); chronic obstructive pulmonary disease (1); colon cancer (1); congenital heart disease (1); hereditary pulmonary alveolar proteinosis (1); intracranial hemorrhage (1); lung carcinoma (1); megakaryoblastic leukemia (1); myeloid leukaemia (1); myeloproliferative disorder (1); rheumatoid arthritis (1); type 2 diabetes (1); viral infection (1).